IL13 (interleukin 13)
Diseases named in the same sentence as IL13 in open-access papers (continued):
Sharing a sentence is not in itself a finding about the gene and the disease.
asthma (continued). "IL-13 is important for the development of T helper cell type 2 (Th2) responses and plays a critical role in asthma and allergy." (PMID 34404340, 2021). "The human interleukin-13-neutralizing monoclonal IgG4 antibody called tralokinumab was tested for different diseases, including severe asthma." (PMID 34572281, 2021). "Targeting TL1A is therefore, more beneficial than targeting IL13/IL4Rα signaling in asthma and muco-secretory disorders." (PMID 34305924, 2021). "Vitamin D is able to suppress the production of proinflammatory cytokines interleukin-17 (IL-17), IL-13 and promote anti-inflammatory IL-10 and Th2 cell activation, hence preventing the onset of asthma development." (PMID 33919626, 2021). "Our results revealed the active ingredients and potential molecular mechanism by which MGMD treatment is effective against airway inflammation and remodeling in asthma through regulating IL-4 and IL-13 signaling and SPMs biosynthesis." (PMID 33968984, 2021). "Screening with a threshold of p-value <0.05 and |LogFC| ≥ 1 led to the identification of 815 DEGs in the IL-13-treated airway epithelial cells and 61 DEGs in the bronchial epithelial cells of asthma patients." (PMID 35126350, 2021). "This review summarizes the IL-4 and IL-13 pathways while highlighting and discussing the current pathway inhibitors aimed at treating thunderstorm asthma and atopic dermatitis, as well as the potential efficacy of peptide therapeutics in this field." (PMID 34948449, 2021). "Many asthma-relevant cytokines, including IL-4, IL-5 and IL-13, depend on JAK signaling to elicit an inflammatory response." (PMID 34680614, 2021). "In asthma, the efficacy of IL-13 antagonists was largely confined to the cohort presenting the IL-13hi biomarker periostin." (PMID 34512647, 2021). "Interleukin-13 (IL-13), secreted by Th2 cells, has been shown to be related to airway inflammation and allergy in asthma." (PMID 34955820, 2021). "Both IL-9 and IL-13 are Th2 cytokines that inhibit the proinflammatory response, but IL-9 promotes mast cell growth and function, and IL-13 mediates allergic inflammation and asthma." (PMID 34339269, 2021). "Asthma has been associated with T helper cell 2 (Th2)-mediated immunity due to aberrant production of IL-4, IL5, and IL13." (PMID 33914833, 2021). "In this sense, the role of dupilumab, a monoclonal antibody blocking IL-4 and IL-13 signaling pathway by inhibiting IL-4R alpha, is promising for the management of patients with asthma with reduced response to corticosteroids, as reviewed recently." (PMID 33816533, 2021). "Eosinophilic inflammatory response, which is characteristic of asthma, is known to be induced by IL-4, IL-5, and IL-13 produced by CD4+ T helper type 2 (Th2) cells." (PMID 34576095, 2021). "Biologics targeting eosinophilic inflammation have been successful for treating severe asthma, and several cytokines, including IL-4, IL-5, and IL-13, have demonstrated promising therapeutic effects in patients with COPD." (PMID 34829866, 2021). "Dupilumab, a monoclonal antibody against human IL-4 receptor α, inhibits both IL-4 and IL-13 signaling and has been confirmed to be effective in phase 3 clinical trials of asthma and atopic dermatitis." (PMID 34194433, 2021). "We have thus sought to gain insight into persistent IL‐13 activity in the peripheral airways of severe asthma through bronchoalveolar lavage analysis." (PMID 33411348, 2021). "Th2 cytokines, such as interleukin-4 (IL-4), IL-5, and IL-13, can initiate and sustain important pathophysiological features of asthma." (PMID 33806085, 2021). "Severe asthma patients with high BAL IL‐13, despite treatment with high‐dose inhaled corticosteroids, had more severe lung function and significantly higher BAL neutrophil percentages, but not BAL eosinophils than those with normal BAL‐13 concentrations." (PMID 33411348, 2021).
asthma (continued). "A whole-transcriptome RNA sequencing study of nasal epithelial cells in children with asthma indicated that the DPP4 gene had a positive relationship with IL-13 mRNA level." (PMID 34955820, 2021). "A slight increase was also evident in JMJD2B protein levels of asthma cells incubated with IL-13 when compared to the control counterparts." (PMID 33688506, 2021). "Blocking IL4/IL-13 yielded promising results in Th-2-induced diseases, such as asthma or atopic dermatitis." (PMID 34831223, 2021). "Researchers developing a new approach of dual IL-13/IL-4 inhibition (dupilumab), reported a therapeutic achievement with a higher clinical relevance for asthma treatment." (PMID 34572281, 2021). "Th2-related cytokines, such as interleukin- (IL-) 4, IL-5, and IL-13, are important for the development of asthma." (PMID 34595240, 2021). "It inhibits bronchial hyperresponsiveness, airway inflammation, and differentiation of T cells toward Th2 in patients with asthma through negative regulation of IL-13 and PPM1A." (PMID 34635022, 2021). "Asthma is a chronic inflammatory disease, and Th2 cells, such as IL-4, IL-5 and IL-13, play key roles in asthma pathobiology." (PMID 35011278, 2021). "In asthma, intranasal miR-140-3p inhibits the inflammatory responses by suppressing the levels of eosinophils and IL-13." (PMID 34872453, 2021). "For instance, IL-17A contributes to asthma pathogenesis and exerts synergistic effects with IL-13 to induce airway hyper responsiveness." (PMID 33441700, 2021). "Ozone has been shown to aggravate AR and asthma by inducing the release of IL-5 and IL-13 from ILC2s." (PMID 34177881, 2021). "This is, therefore, one of the first reports indicating the involvement of IL-13-mediated JMJD2B expression in the pathogenesis of asthma." (PMID 33688506, 2021). "The Reactome pathway analysis showed that MGMD prevents asthma mainly through regulation of the IL-4 and IL-13 signaling and the specialized pro-resolving mediators (SPMs) biosynthesis." (PMID 33968984, 2021). "For example, treatment with a monoclonal human anti-IL-4Rα antibody dupilumab (which inhibits both IL-13 and IL-4 signaling) has shown significant benefits in patients with otherwise uncontrollable asthma or severe dermatitis." (PMID 34027204, 2021). "Th2 cytokines, including interleukin (IL)‐4 and IL‐13, are closely related to various allergic diseases including asthma." (PMID 33534941, 2021). "Each cytokine has distinct functional effects in the induction of disease, but IL-13 predominates in its contribution to the pathophysiology in asthma." (PMID 33914833, 2021). "In turn, increased PI3Kγ activity is responsible for IL-13-mediated contraction of airway smooth muscle (ASM) cells, the underlying mechanism of AHR induced by allergen sensitization or cytokines in asthma." (PMID 33821232, 2021). "In contrast, asthma pro-inflammatory cytokines such as IL-4, IL-5, IL-13, and IL-33 contribute to maintain the lean state." (PMID 33418879, 2021). "IL-13 is a key factor of type 2 immunity and plays an important role in fighting helminth infection, regulating asthma and tissue repair." (PMID 34604237, 2021). "Atopic diseases such as atopic dermatitis, allergic rhinitis, and asthma involve an uncontrolled type 2 inflammatory response mediated by the Th2 cytokines IL-5, IL-13, and IL-4." (PMID 34238943, 2021). "The application of monoclonal antibodies against IL‐13, such as tralokinumab and dupilumab, has been investigated in the treatment of asthma." (PMID 33943014, 2021). "Recently, it has been demonstrated that IL‐13 alters the tight junctions of cutaneous and bronchial epithelia in AD and asthma, respectively." (PMID 34617355, 2021). "Our previous study has developed a four‐gene model involving IL13 rs20541, IL4 rs2243250, ADRB2 rs1042713, and FCER1B rs569108 associated with asthma and atopy in Chinese Han children." (PMID 33277970, 2021).
asthma (continued). "Since IL-13 plays a central role in the pathogenesis of asthma, we used bioinformatics to identify novel IL-13- regulated epigenetic modifiers in asthma." (PMID 33688506, 2021). "In the current study, IL-13 predominated in its contribution to the pathophysiology in asthma, and the regulation of IL-13 expression and release by Vinp contributed to alleviating the pathophysiological changes." (PMID 33914833, 2021). "The activation of Th2 lymphocytes is a significant factor in the development of asthma, which can stimulate the synthesis of IgE and the infiltration of inflammatory cells by releasing representative cytokines such as IL-13, IL-4, and IL-5." (PMID 33628113, 2021). "Nowadays, available biological asthma therapy is reserved for T2-high asthma; it targets allergy molecules IgE and eosinophilic interleukins (IL-5, IL-4, IL-13, TSLP)." (PMID 34070316, 2021). "IL-13 also augmented the demethylation of histone H3, suggesting a potential mechanism involving JMJD2B in IL-13-mediated activation of fibroblasts which plays an important role in promoting fibrosis as well as inflammatory processes in asthma." (PMID 33688506, 2021). "For instance, a dietary intervention with 1% GOS suppressed the increased BALF leukocyte numbers and CCL5 and IL-13 levels in a murine house dust mite-induced asthma model." (PMID 34684515, 2021). "Among these factors are several key actors of type-2 immunity and tissue remodeling with a suspected role in asthma, most notably IL-4, IL-13, and transforming growth factor (TGF)-β1." (PMID 34576313, 2021). "The best known endotype of asthma is type-2-high asthma, characterized by airway and blood eosinophilia, and the presence of biomarkers that depend on the type 2 cytokine IL-13, such as exhaled nitric oxide (FeNO)." (PMID 34627360, 2021). "The IL‐13 response genes, which are upregulated in central airway bronchial epithelial of asthma patients, can be normalized by high‐dose inhaled steroid therapy in severe asthma." (PMID 33411348, 2021). "Dupilumab is an IL4-Rα antibody that has been used in atopic dermatitis, severe asthma, and chronic rhinosinusitis and inhibits Th2 cytokine signalling via IL-4 and IL-13." (PMID 34729149, 2021). "While the roles of SPRR1B and SPRR3 in asthma are unclear, it has been shown that the members of the SPRRs family SPRR2A and SPRR2B are upregulated in an IL-13-dependent manner in an allergen-induced asthma model." (PMID 35126350, 2021). "Since the involvement of IL-13-mediated epigenetic regulation of subepithelial fibrosis in asthma is not clearly understood, we employed bioinformatics to identify novel IL-13 regulated epigenetic modifiers in asthma." (PMID 33688506, 2021). "In the current study, we aimed to investigate the expression of Fbp1 in a murine model of asthma and interleukin (IL)‐4‐stimulated or IL‐13‐stimulated airway bronchial cell lines." (PMID 33960626, 2021). "Eighty percentage of children and 60% of adults with asthma have type 2/Th2 asthma, which is driven by allergen-induced production of IgE and Th2 cytokines, including IL-5, IL-13, and IL-4." (PMID 33643321, 2021). "Group 2 innate lymphoid cells (ILC2s) are an important source of type 2 cytokines IL-5 and IL-13, which contribute to the progress of asthma." (PMID 34305612, 2021). "Gene Expression Omnibus (GEO) data sets revealed that Fbp1 was overexpressed in a murine model of asthma and in interleukin (IL)‐4‐ or IL‐13‐stimulated bronchial epithelial cells." (PMID 33960626, 2021). "First, a phase I clinical trial was reported for dry powder inhaled formulation of VR942 (abrezekimab), a monoclonal antibody fragment used to treat asthma by inhibition of interleukin-13." (PMID 34467438, 2021). "Despite the well-recognized immunopathobiology of IL-13 in asthma, clinical trials of anti-IL-13 monoclonal antibodies (mAbs) in patients with severe asthma have been largely ineffective." (PMID 33688506, 2021).
asthma (continued). "The BM-MSCs IT injection in OVA-induced asthma decreased eosinophilia, lymphocyte, total protein, IL-13, and IL-17A levels and significantly decreased airway remodeling, which persisted for 14 days after the injection." (PMID 33959015, 2021). "Unfortunately, no studies thus far have looked at the efficacy of combining anti-IL-4/IL-13 and anti-IL-5 biologics for asthma treatment." (PMID 35126131, 2021). "As the common receptor for both IL-4 and IL-13 signaling, blockade of IL-4 receptor alpha (IL-4Rα) has been touted as a method of alleviating asthma symptoms and severity." (PMID 33653328, 2021). "IL-4 and IL-13 are thought to play an important role in asthma pathogenesis by inducing eotaxin (an eosinophil chemoattractant), increasing mucin glycoproteins (and causing mucous hyperplasia), and augmenting IgE-related hypersensitivity reactions." (PMID 33653328, 2021). "IL-33 is mainly secreted by the airway epithelium and evidenced to exacerbate the Th2-mediated inflammation via further promoting the secretion of IL-4, IL-5, and IL-13 in allergic patients with asthma." (PMID 32650472, 2020). "Although anti-IL-5 treatment and anti-IL-4/IL-13 treatment are clinically available for treating eosinophil-dominant severe asthma, recent research has been mainly focused on molecules that are more upstream, such as thymic stromal lymphopoietin." (PMID 32326200, 2020). "In clinical asthma cases, there are high IL-13 levels observed in BALF that induce AHR and difficulty of breathing." (PMID 33343229, 2020). "It is well recognized that asthma is an immune response driven by Th2 and Th17 cells with cytokines such as IL-4, IL-5, IL-9, IL-10, IL-13, and IL-7 playing important roles." (PMID 33123005, 2020). "Periostin, a matricellular protein produced by airway epithelial cells under the control of IL-4 and IL-13, is a key molecule linking TType2/eosinophilic airway inflammation and remodeling in asthma." (PMID 32824775, 2020). "It turned out that the mRNA expressions of several inflammatory factors, such as tumor necrosis factor (TNF), Muc5ac, IL-4, IL-13, and IL-12b were significantly upregulated in asthma group compared with control and diacerein groups." (PMID 33013396, 2020). "Oral administration of C. sativus extract (1 and 10 mg/kg, p.o.)and safranal in the OVA-induced murine model of asthma (in vitro) study, reduced iNOS levels and inflammatory cytokines such as; L-5 and IL-13 levels in the lung tissue." (PMID 33295229, 2020). "This repression of miRNA levels was induced by IL-13 resulting in increased notch expression as well as mucous cells increase in asthma." (PMID 32770056, 2020). "The findings suggested that OVA exposure contributed to the remarkable elevation of IL-4, IL-5, IL-13, and IL-17A level in asthma group mice compared with control group mice." (PMID 33013383, 2020). "Quantification of IL-13 in mild to severe asthma patients reveals high serum concentration that promotes changes in cellularity, IgE concentration, and decreased lung function (FEV1)." (PMID 32366038, 2020). "When relatively low levels of LPS are inhaled, a cascade of immune responses leads to Th2 cell induction, and IL-5 and IL-13 released by Th2 cells contributes to asthma development." (PMID 32203101, 2020). "IL-13-producing CD8+ T cells have been associated with the induction and progress of asthma, as well as contact allergy dermatitis." (PMID 33311473, 2020). "Naïve T cells turn into Th2 cells, releasing a set of cytokines (IL-4, IL-5, and IL-13), which triggers the characteristic processes of asthma." (PMID 33488613, 2020). "Cultured ASMCs exposed to IL-13 and/or IL-17A showed a robust transcriptional response to these asthma-promoting cytokines." (PMID 32690065, 2020).
asthma (continued). "Our results display that both T cells and ILCs seem to contribute to the production of IL-5 and IL-13 when OVA in alum induced asthma, suggesting both immune response pathways of Th2 cells and ILCs can be therapeutic targets for preventing or treating asthma." (PMID 33374657, 2020). "In the present study, this application was demonstrated by using IL-13 treatment to simulate chronic airway contractile regulation in asthma." (PMID 32296115, 2020). "For instance, Th2 cells secrete cytokines such as IL-4, IL-5, and IL-13 and play important downstream roles in the pathogenesis of asthma." (PMID 32580518, 2020). "The cytokines of IL-4, IL-5, and IL-13 produced by Th2 cells are deeply involved in IgE synthesis, eosinophil activation, mucus secretion, and airway remodeling during the pathogenesis of asthma." (PMID 33192556, 2020). "It is worth mentioning that silver NPs have been shown to mitigate asthma and decrease the levels of IL-4, IL-5, IL-13, and NF-κB in addition to lowering AHR in OVA-induced allergic inflammation mouse models." (PMID 32714326, 2020). "For example, the migration of human airway smooth muscles has been confirmed to be regulated by cytokines, including IL-13 and IL-17, and further contribute to the pathogenesis of asthma." (PMID 33519902, 2020). "The alpha subunit of the IL-4 receptor (dupilumab), that blocks both IL-4 and IL-13 pathways, has resulted in reduction of asthma morbidity, while the use of the anti-IL-4R failed in phase II." (PMID 32194407, 2020). "IL-13 is a drug target in several inflammatory diseases, including asthma, atopic dermatitis, and inflammatory bowel disease." (PMID 32235914, 2020). "Numerous studies have shown that IL-13 is a central regulator of T-helper type 2 (Th2)-dominated disorders such as asthma, and some studies have suggested that IL-13 blockade prevents allergen-induced airway inflammation." (PMID 32824013, 2020). "Immunological treatment with monoclonal antibodies against anaphylactic IgE or against type 2 cytokines such as IL-5 and IL-4/IL-13 is another way to control asthma symptoms." (PMID 32391011, 2020). "Topological data analysis using human epithelial transcriptomic data from the U‐BIOPRED cohort identified severe asthma groups with features consistent with the presence of IL‐13 and EGFR/ERBB activation, with involvement of distinct EGFR ligands." (PMID 32096290, 2020). "In animal models, lung epithelial cell-derived exosomes enhance the infiltration of macrophages and production of IL-13, leading to the development of asthma." (PMID 32641036, 2020). "Administration of ascorbic acid and calcitriol in effective doses significantly decreased IL-13 levels in comparison with the asthma group (42.73 ± 0.27 vs. 50.5 ± 1.85 pg/mL, p = 0.009 and 43.24 ± 0.37 vs. 50.5 ± 1.85 pg/mL, p = 0.04, respectively)." (PMID 31942829, 2020). "Inhibiting the biological effects of both IL4 and IL13 with the monoclonal antibody dupilumab has been shown to markedly decrease asthma exacerbations and improve lung function." (PMID 33506093, 2020). "The activation of ILC2 leads to the release of IL-9, IL-4, IL-13, and IL-5, and to Th2 type inflammation both in asthma and CRS." (PMID 33322143, 2020). "Recently, a specific study on the relationships between asthma-promoting cytokines (IL-13 and IL-17) and ASMCs tried to identify key regulatory factors on the transcriptomics and epigenetics levels." (PMID 33519902, 2020). "The Th2 response plays a significant role in asthma, leading to interleukin-4 (IL-4), IL-5, and IL-13 production, IgE-mediated responses, mucus secretion and airway hyperreactivity (AHR)." (PMID 32620122, 2020). "In the lungs of patients with asthma, Th2 cells secrete excess IL-4, IL-5, and IL-13 to inhibit the expression of Th1 cells, which reduces IFN-γ secretion." (PMID 32244835, 2020).